OR5G3 (olfactory receptor family 5 subfamily G member 3 (gene/pseudogene))
Description:
Odorant receptor.
Synonyms: OR5G3P; OR5G6P
Gene: Protein-coding gene on chromosome 11 (56,819,573 to 56,820,516, reverse strand). Ensembl gene ENSG00000241356.
Subcellular location: Cell membrane
Pathways (Reactome):
Sensory Perception: Expression and translocation of olfactory receptors
Homologues: Orthologues: mouse Or5d20 (22% identical). Paralogues in human: OR5B12 (32% identical), OR5B21 (32% identical), OR5B2 (30% identical), OR5B3 (30% identical), OR5F1 (30% identical), OR5B17 (30% identical), OR5AP2 (29% identical), OR5J2 (28% identical), OR5A1 (27% identical), OR5AS1 (27% identical), OR5C1 (27% identical), OR5A2 (27% identical), and 84 more.